TMEM101 (transmembrane protein 101)
Description:
May activate NF-kappa-B signaling pathways.
Synonyms: MGC4251; FLJ23987
Tractability: Antibody: UniProt predicts a signal peptide or a membrane-spanning region; the Human Protein Atlas places it where antibodies can reach.
Gene: Protein-coding gene on chromosome 17 (44,011,188 to 44,023,946, reverse strand). Ensembl gene ENSG00000091947.
Subcellular location: Membrane
Subcellular location (Human Protein Atlas): Nucleoplasm; Plasma membrane
Gene Ontology:
Molecular function: protein binding
Biological process: positive regulation of canonical NF-kappaB signal transduction
Cellular component: membrane
Genetic constraint (gnomAD): Loss-of-function variants: 14 observed, 23.24 expected, observed/expected ratio (o/e) 0.6, 90% interval 0.4 to 0.94. The upper end of that interval is the gene's LOEUF score, 0.94, which puts it in group 3 of 6, group 1 being the genes least tolerant of losing a copy. Missense variants: 292 observed, 330.58 expected, observed/expected ratio (o/e) 0.88, 90% interval 0.8 to 0.97. Synonymous variants: 152 observed, 134.89 expected, observed/expected ratio (o/e) 1.13, 90% interval 0.99 to 1.29.
Homologues: Orthologues: chimpanzee TMEM101 (100% identical), macaque TMEM101 (99% identical), dog TMEM101 (98% identical), mouse Tmem101 (98% identical), pig TMEM101 (98% identical), rabbit TMEM101 (98% identical), guinea pig TMEM101 (95% identical), rat Tmem101 (83% identical), tropical clawed frog pyy (76% identical), zebrafish tmem101 (71% identical).
Diseases named in the same sentence as TMEM101 in open-access papers:
TMEM101 is named in the same sentence as 8 diseases in open-access papers, as found by Europe PMC text mining. Sharing a sentence is not in itself a finding about the gene and the disease. The quoted sentences say what the papers report.
breast carcinoma (2 papers, 2023 to 2024). "For instance, four CpGs within the same CpG island of TMEM101, a potential biomarker for reduced overall survival in breast cancer patients, were hypermethylated in UCEC but not in other cancer types." (PMID 38336771, 2024).
bladder cancer (1 paper, 2024). "Further studies are required to determine whether hypermethylation of TMEM101 and RAI1 could be used as biomarkers for the screen and diagnosis of endometrial and bladder cancer, respectively." (PMID 38336771, 2024).
melanoma (1 paper, 2023). A malignant, usually aggressive tumor composed of atypical, neoplastic melanocytes. "The gene-signature contained three genes, including TRIB3, TMEM101, and SLC12A9, of which some have been reported to be correlated to melanoma and other tumors." (PMID 37268878, 2023).
ovarian clear cell cancer (1 paper, 2025). An invasive malignant neoplasm that arises from the ovary and is characterized by a predominance of clear and hobnail malignant epithelial cells. "Interestingly, this phenomenon mirrors the findings in ovarian clear cell carcinoma, where ARID1A mutations are associated with promoter hypermethylation and transcriptional repression of downstream targets such as IRX1, TMEM101, and TRIP6." (PMID 41215803, 2025).
stomach adenocarcinoma (1 paper, 2024). "CpGs located in the same CGI of TMEM101 (n = 4) and RNLS (n = 2) were hypermethylated in uterine corpus endometrial carcinoma and stomach adenocarcinoma, respectively." (PMID 38336771, 2024).
cancer (3 papers, 2021 to 2024). A tumor composed of atypical neoplastic, often pleomorphic cells that invade other tissues. "We identified 12 genes that were significantly differentially expressed in R compared to NR patients across the three cancer types, comprising 10 downregulated genes and 2 upregulated genes (ANXA4, TMEM101)." (PMID 34921236, 2021). "There is to our knowledge no previous literature suggesting a role of TMEM101 promoter methylation in relation to cancer progression/survival." (PMID 33461604, 2021).
tumour (1 paper, 2021). "We found that promoter hypermethylation at APC, TMEM101 and HCG4P3 was associated with shorter overall survival in the MCCS after adjustment for age and tumour stage." (PMID 33461604, 2021). "After adjusting for age at diagnosis and tumour stage, the association remained consistent for APC (HR = 1.24, 95% CI: 1.04–1.49), TMEM101 (HR = 1.22, 95% CI: 0.99–1.51) and HCG4P3 (HR = 1.25, 95% CI: 0.91–1.72)." (PMID 33461604, 2021). "In the MCCS, higher tumour methylation showed association with shorter overall survival for APC (HR = 1.28, 95% CI: 1.07–1.53), HIST3H2A/HIST3H2BB (HR = 1.28, 95% CI: 1.02–1.62), CELF2 (HR = 1.30, 95% CI: 1.07–1.58) and TMEM101 (HR = 1.21, 95% CI: 1.00–1.48)." (PMID 33461604, 2021).
TMEM101 also shares sentences with these, for which no sentence is quoted: uterine corpus endometrial carcinoma (1 paper).